MMP9 (matrix metallopeptidase 9)
Diseases named in the same sentence as MMP9 in open-access papers (continued):
Sharing a sentence is not in itself a finding about the gene and the disease.
gastric cancer (395 papers, 1996 to 2026). A primary or metastatic malignant neoplasm involving the stomach. "Several meta-analyses and bioinformatic studies have found that the overexpression of MMPs, like MMP2 and MMP9, is associated with a poor prognosis in gastric cancer patients." (PMID 40906383, 2025). "The gelatinases MMP2 and -9 are crucial in invasion and metastasis and in several tumor entities, and the MMP9 promoter allele Rs3918242 is associated with a higher risk of metastasis in gastric cancer." (PMID 35269560, 2022). "They proved that melatonin suppressed cell growth by directly reducing ROS production, while indirectly decreasing the level of MMP2 and MMP9 in cancer-associated fibroblasts (CAFs) in gastric cancer cells." (PMID 36591447, 2022). "In MMP-9 gene promoter, a -1562 C/T polymorphism has been suggested to be associated with degree of tumor invasion and clinical stage of gastric cancer patients." (PMID 35163805, 2022). "There are quite a few studies, which analyzed the association of MMP gene polymorphisms with gastric cancer and reported such an association for the MMP9 gene SNPs included in our study (rs3918242, rs17576, rs17577)." (PMID 34492072, 2021). "As exhibited in the previous studies, decreased MMP-2 and MMP-9 expression has been shown to be associated with inhibited metastatic capacity in multiple human tumors, such as gastric cancer, colon cancer, ovarian cancer and HNSCC." (PMID 34587874, 2021). "In fact, it has been recently proven that TRPM2 causes an increase in MMP-9 production in gastric cancer." (PMID 33132914, 2020). "PI3K/AKT/β-catenin transcriptionally activates VGLL1, thus calibrating MMP9 expression linked to gastric cancer malignancy." (PMID 31816819, 2019). "We chose a total of nine papers to estimate the association of MMP-9 polymorphisms with gastric cancer." (PMID 29228747, 2017). "Our datas found that FOXO6 was positively associated with the expression of MMP-9 in gastric cancer." (PMID 28404958, 2017). "A computerised literature search was conducted within the databases of PubMed, EMBASE, and ISI Web of Knowledge for studies on the genetic association of MMP-9-1562C/T and gastric cancer published from 2004 to 2015." (PMID 29228747, 2017). "The results by Japanese researchers in 2005 indicated that the T allele in the MMP-9 promoter is associated with the invasive phenotype of gastric cancer." (PMID 29228747, 2017). "In conclusion, the results of our meta-analysis demonstrated that promoter region polymorphisms of the MMP-9 gene were associated with the susceptibility of gastric cancer." (PMID 29228747, 2017). "Our data revealed that FOXO6 was significantly associated with MMP-9 expression in 192 gastric cancer samples (r = 0.503, P < 0.001)." (PMID 28404958, 2017). "Our meta-analysis results demonstrated that MMP-9-1562C/T promoter polymorphisms increase the risk of developing gastric cancer." (PMID 29228747, 2017). "Overexpression of MMP9 has been found in various tumors, and recently an association with a poor prognosis in osteosarcoma and oral and gastric cancer has been proved." (PMID 28326100, 2017). "In the present study, we tested the effects of chrysin on MMP-9 expression in gastric cancer cells, and determined its underlying mechanism." (PMID 25875631, 2015). "In the present study, we investigated the inhibitory effect of chrysin on MMP-9 expression and revealed the underlying mechanism in gastric cancer AGS cells for the first time." (PMID 25875631, 2015). "In the present study, we investigated chrysin’s effects on PMA-induced MMP-9 expression in gastric cancer, and revealed its underlying mechanism." (PMID 25875631, 2015). "The data indicates that MMP-9 has potential as a diagnostic marker and therapeutic molecular target for management of gastric carcinoma." (PMID 25621068, 2015). "The association between HSP60 and MMP-9, clinicopathological parameters, and prognosis of gastric cancer was examined." (PMID 25207654, 2014).
gastric cancer (continued). "In gastric cancer, lymphatic dissemination and lymph-node metastasis associate with increased expression of both Twist and gelatinase B/MMP-9." (PMID 24473089, 2014). "The association between expression of ALDH1A1 and MMP-9, clinicopathological parameters, and prognosis of gastric cancer was examined." (PMID 25253129, 2014). "Although no studies have yet reported on COL10A1, ADA, or LHFP and cancer survival, CTSB and MMP9 have both been previously associated with survival in gastric cancer, while ESRRG expression has been associated with survival in prostate cancer." (PMID 23717493, 2013). "MMP9 plays a critical role in maintaining the degradation and synthesis of extracellular matrix, and was shown to be positively associated with gastric cancer cell metastasis in animal models and human gastric cancers." (PMID 23402362, 2013). "IL-8 treatment increases the invasive capacity of gastric cancer cells, and IL-8 expression is associated with MMP-9 activity." (PMID 20369064, 2010). "MMP9 is upregulated across multiple stages, including primary tumors, intestinal metaplasia, gastritis, and atrophy, with its expression linked to tumor invasion and metastasis in advanced gastric cancer." (PMID 40141751, 2025). "It is thought that H. pylori-associated GU is positively linked to stomach cancer due to the damage of gastric mucosa and the MMP9 gene may be one of the candidate genes involved in both H. pylori-associated GU and gastric cancer." (PMID 34492072, 2021). "The study results suggest that MMP-9 expression could be a potential biomarker of aggressive gastric cancer and candidates for the possible diagnostic and prognostic tool." (PMID 34707964, 2021). "Also, a closer look at the mechanism of action between semaphorin, LOX, and MMP-9 can reveal new pathways in gastric cancer invasion and its association with the EMT pathway." (PMID 34054953, 2021). "However, the association between MMP-9 SNPs and gastric cancer has been established in the Chinese population, especially rs17576 and rs2250889 SNPs are significantly associated with lymph node metastases, especially in diffuse type gastric cancer." (PMID 33146350, 2020). "In addition, a number of meta-analyses found that overexpression of MMPs was associated with poor prognosis in gastric cancer patients, as was the case for MMP-9 and MMP-2." (PMID 32046329, 2020). "Some members of the MMP family, especially MMP-2 and MMP-9, known as gelatinases A and B, are critically involved in tumor invasion, and metastasis and their expression have been associated with poor overall survival in patients with gastric cancer." (PMID 31817563, 2019). "In addition, human astrocytoma cells expressed increased levels of fibronectin and VEGF upon transformation with a versican G3 construct and VEGF expression was positively linked to MMP-9 levels in gastric carcinoma." (PMID 31261642, 2019). "More comprehensive studies may eventually result in a better understanding of the association of MMP-9-1562C/T polymorphisms with gastric cancer." (PMID 29228747, 2017). "Previous study found that MMP-9 expression was associated with aggressiveness in gastric cancer." (PMID 28404958, 2017). "It has been reported that MMP-9 was associated with aggressiveness in gastric cancer." (PMID 28060752, 2017). "Furthermore, we found that MLN4924 blocks migration of gastric cancer cells which is associated transcriptional induction of E-cadherin and repression of MMP-9." (PMID 27063292, 2016). "In contrast, overexpression of THBS1 in stromal myofibroblasts is associated with tumour growth and nodal metastasis in gastric carcinoma, and may promote tumour cell invasion via upregulation of MMP-9 expression by endothelial cells." (PMID 25652121, 2015). "Among the MMPs, MMP-9 has a close association with tumor metastasis, and is considered, in particular, to be an important factor in facilitating invasion and metastasis in gastric carcinoma." (PMID 24137341, 2013).
gastric cancer (continued). "In addition, HSP90 protein expression was significantly associated with MMP-9 expression in 322 gastric carcinoma tissues." (PMID 23638161, 2013). "Finally, a significant association in Japanese gastric cancer patients was found between an SNP in the promoter of the MMP-9 gene (−1562C>T) and the degree of tumour invasion, clinical stage and lymphatic invasion." (PMID 16940985, 2006). "The association between MMP-9 and early stages of gastric carcinoma was also present in our study." (PMID 16538217, 2006). "In addition, an elevated expression of MMP-9 and downregulation of E-cadherin have been found to associate with poorly differentiated gastric carcinoma and lymph-node metastasis, and together with increased levels of VEGF and MMP-2, they can serve as malignancy markers in gastric cancer." (PMID 35163805, 2022). "In our study, we found that MMP9 levels are significantly elevated in gastric cancer tissues compared to adjacent normal mucosa." (PMID 41041068, 2025). "MMP9 has been positively correlated with the depth of gastric cancer invasion, and higher levels of MMP9 have been reported in the serum of gastric cancer patients compared to controls." (PMID 40906383, 2025). "Mechanistically, TSPAN9 suppresses the secretion of metastasis-associated proteins, such as MMP9, through inhibition of the ERK1/2 pathway, thereby impairing gastric cancer cell proliferation, migration and invasion." (PMID 40643467, 2025). "USP19, which belongs to the category of potential pro-cancer factors, enhances the MMP2/MMP9 axis and related enzyme activities in patients with gastric cancer." (PMID 40280943, 2025). "The target proteins implicated in gastric cancer, specifically HIF1A, HSP90AA1, MMP9, ERBB2, and PTGS2, were matched with the key metabolites from the Vaccinium genus, including cyanidin 3-O-glucoside, ursolic acid, resveratrol, scopoletin, and (+)-catechin." (PMID 40141751, 2025). "The development, spread, and metastasis of breast, lung, colon, and stomach cancers are all greatly affected by MMP-9." (PMID 40563423, 2025). "A recent study found that S100A4 can promote the invasion and metastasis of gastric-cancer cells by upregulating the expression of MMP9." (PMID 39852172, 2025). "The RNA sequencing data highlight several key proteins—HIF1A, HSP90AA1, PTGS2, MMP9, and ERBB2—which are associated with various stages of gastric cancer progression and align with established biomarkers and pathways." (PMID 40141751, 2025). "Western-blotting was used to detect the protein expression of EMT/ metastasis related markers MMP-2, MMP-9, N-cadherin, Zeb1, Vimentin, Snail and E-cadherin in gastric cancer cells." (PMID 40265472, 2025). "The link between SLPI and MMP-9 was reported in the context of cancer cell lines where it has been shown that SLPI can either limit MMP-9 secretion in ovarian cancer or promote MMP-9 in gastric cancer." (PMID 40496854, 2025). "This indicates that the upregulation of MMP9 activity can mediate the immune escape against NK cells by increasing the levels of soluble ligands such as sMICA in gastric cancer cells." (PMID 40563539, 2025). "This process is mediated by enzymes known as matrix metalloproteinases (MMPs), particularly MMP-2 and MMP-9, which are often overexpressed in gastric cancer." (PMID 39906672, 2024). "The ability of KXAN to reduce the protein level of MMP-9 in gastric cancer cells was also described previously." (PMID 39201397, 2024). "For instance, SIRT2 activates the RAS/ERK/JNK/MMP-9 pathway in gastric cancer to raise PEPCK1 protein levels, mitochondrial activity, and cell migration and invasion." (PMID 39479446, 2024). "H and colleagues conducted an investigation into the relationship between neurotensin (NT) and matrix metalloproteinase-9 (MMP-9) in gastric cancer." (PMID 39409942, 2024).
gastric cancer (continued). "In gastric cancer, increased PCK1 levels promote the TCA cycle, activate the RAS/extracellular signal-regulated kinase (ERK) signaling pathway, induce MMP-9 expression, and eventually lead to gastric cancer metastasis." (PMID 39578429, 2024). "Inflammatory molecule IL-6, cell cycle regulator C-Myc, cell migration molecule MMP-9, and apoptosis molecule Caspase-3 exhibit significantly higher expression levels in the Gastric cancer group compared to the Control group (P < 0.01)." (PMID 38301047, 2024). "By inhibiting Grhl2 expression, TGF-β can promote MMP-2, MMP-7, and MMP-9 expression in gastric cancer, thereby facilitating the invasion and migration of gastric malignant cells." (PMID 38818471, 2024). "In Wilms’ tumor and gastric cancer, MMP-9 is upregulated in M2 macrophages, and MMP-9 initiates EMT and increases tumor cell invasion." (PMID 39555068, 2024). "It has been confirmed that high expression of Ki‐67 and MMP‐9 contributes to gastric cancer development." (PMID 39524138, 2024). "Conversely, the concurrent presence of integrin αvβ6 and Matrix Metallopeptidase 9 (MMP-9) is a reliable predictive marker in individuals diagnosed with gastric cancer." (PMID 38818471, 2024). "Although previous study has demonstrated that AhR activation increased Mmp9 expression in gastric cancer cells, our study found that SCFAs supplementation promoted AhR activation and suppressed the expression of Mmp9 in EAE mice." (PMID 38976012, 2024). "PrPC overexpression increases matrix metalloprotease-9 (MMP-9) expression by enhancing the association of NF-κB with the promoter of the MMP-9 gene and ERK signaling, similar to that observed in gastric cancer." (PMID 37894349, 2023). "AQP3 overexpression increased MMP-3 secretion in prostate cancer cells and MT1-MMP, MMP-2, and MMP-9 in gastric cancer cells." (PMID 37681917, 2023). "In concentrations below 10 μM, EA effectively suppressed MMP-7 and MMP-9 expression triggered by acidity, restraining the migratory and matrigel-infiltrating capacity of gastric cancer cells." (PMID 38002335, 2023). "The findings revealed that magnolol and cisplatin dramatically reduced gastric cancer cell migration, which correlated to a reduction in MMP-9 expression." (PMID 36837487, 2023). "In general, it was found that Luteolin exerted its biological properties by inhibiting Cyclin D1, Cyclin E, Bcl2, MMP-2, MMP-9, N-cadherin, Vimentin, and inducing p21, Bax, and E-Cadherin expressions in gastric cancer cells." (PMID 36992138, 2023). "In human stomach cancer cells, up-regulation of AQP3 was associated with the increased expression of MMP2 and MMP9." (PMID 37143707, 2023). "Activation of β2-ARs by isoproterenol in A549 cells was shown to increase the expression of MMPs, including MMP9, a finding also observed in pancreatic and gastric cancer." (PMID 37760996, 2023). "Monoclonal antibodies developed against MMP9 have been studied in many cancers, of which moderate efficacy has been observed in gastric carcinoma when given along with cytotoxic drugs." (PMID 36756017, 2023). "These properties make DHCE a promising candidate drug for the further design and development of novel and effective Ras/Raf/ERK/MMP9 pathway inhibitors for treating gastric cancer." (PMID 35566048, 2022). "We revealed that nicotine induces MMP-9 expression and cell invasiveness in gastric cancer AGS cells." (PMID 35563563, 2022). "It will be a drug candidate for the design and development of gastric cancer therapeutic inhibitors targeting the Ras/Raf/ERK/MMP9 pathway." (PMID 35566048, 2022). "The combined expression of αvβ6 and MMP-9 (Matrix metallopeptidase 9) proved to be an effective prognostic indicator in patients suffering from gastric cancer." (PMID 36293202, 2022). "The delivery of miR-7 abolished the activity of NF-κB; expression of its transcriptional targets, namely ICAM-1, VCAM-1, vimentin, VEGF, MMP-2 and MMP-9; and mitigated gastric cancer metastasis in the lung and liver." (PMID 35163805, 2022).
gastric cancer (continued). "EGCG suppresses recepteur d’origine nantais (RON) expression in gastric cancer cells by inhibiting Egr-1 (-) and blocked MMP-9 expression induced by nicotine in endothelial cells." (PMID 36430487, 2022). "TAMs-produced MMP-9 activates the PI3K/AKT/Snail signaling in gastric cancer cells and promotes their motility, most likely via repressing E-cadherin expression." (PMID 35163805, 2022). "A recent study proved that c-Fos played a critical role in metastasis in gastric cancer, and c-Fos binding sites of the MMP-9 promoter were activated by p38." (PMID 35537818, 2022). "In terms of mechanism, WSP can inhibit the downstream EGFRVIII signaling pathway Akt-PI3K and further inhibit the secretion of cancer-related metastasis proteins such as MMP2 and MMP9, thus, significantly affecting the metastasis of gastric cancer cells." (PMID 36568183, 2022). "The elevated levels of VEGF and VEGFR-1, as well as MMP-9 and MMP-2, have been linked to the formation of VM in gastric cancer tissues." (PMID 35747793, 2022). "Sulforaphane effectively suppressed ROS, p38 MAPK, Erk1/2, AP-1, and NF-κB activation by inhibiting MMP-9 expression in gastric cancer AGS cells." (PMID 35563563, 2022). "Targets and pathways analysis showed that the Ras/Raf /ERK/MMP9 cascade is essential to the growth, proliferation, survival, invasion, and migration of gastric cancer cells." (PMID 35566048, 2022). "MMP-9 rs3918242 was remarkably related to gastric cancer (GC) incidence among the Asian populations in the recessive model (OR = 1.612, 95% CI = 1.000–2.598, p = 0.05)." (PMID 35574300, 2022). "Another more recent study demonstrated that direct contact between platelets isolated from patients with advanced gastric cancer and gastric cancer tumor cells induced processes of migration, invasion, adhesion, and expression of MMP9 in tumor cells." (PMID 35207103, 2022). "Here, we found that sulforaphane suppresses the nicotine-mediated induction of MMP-9 in human gastric cancer cells." (PMID 35563563, 2022). "Early studies have demonstrated an enhanced expression and activity of MMP-2 and MMP-9 in human gastric carcinoma in comparison to adjacent tissue and have suggested them as prognostic markers of a poor overall survival of patients." (PMID 35163805, 2022). "The RT-PCR data revealed an increased expression of MMP-13, which can be activated by MMP-2 and can activate MMP-9 in gastric carcinoma specimens, in comparison to normal control samples." (PMID 35163805, 2022). "For example, it promotes gastric cancer metastasis via interaction with Arp2, MMP-9, and cathepsin K, increases matrix degradation and invasion and decreases adhesion and formation of invadopodia-like extensions in glioblastoma cells." (PMID 34179087, 2021). "We have previously shown that miR-200c targets VEGFR and MMP9 in gastric cancer cell lines and miR-200c inhibits CXCR4 indirectly by targeting ZEB1." (PMID 33673143, 2021). "We also proved that the anti-MUC1 antibody with OM-86II decreased the concentrations of MMP-9, sICAM1 and mTOR in gastric cancer cells." (PMID 34770912, 2021). "Accordingly, a recent study has shown that direct contact between platelets isolated from advanced gastric cancer patients and gastric cancer cells particularly induced migration, invasion, adhesion, and MMP9 expression in the tumor cells." (PMID 33791226, 2021). "Another study showed that the metastasis of gastric cancer cells was induced by MMP9, and this process was activated by the PI3K-AKT signaling pathway." (PMID 34899944, 2021). "Immunohistochemical studies indicate overexpression of MMP-2 and MMP-9 in 78% and 70% of all tested stomach cancer samples, respectively." (PMID 34770912, 2021). "This study aims at the correlation of MMP-9 expression in gastric cancer with existing prognostic factors." (PMID 34707964, 2021).